SLC25A13 (solute carrier family 25 member 13)
Diseases named in the same sentence as SLC25A13 in open-access papers (continued):
Sharing a sentence is not in itself a finding about the gene and the disease.
colorectal cancer (3 papers, 2016 to 2022). A primary or metastatic malignant neoplasm that affects the colon or rectum. "We showed that SLC25A13 was negatively associated with the depth of tumor invasion, extent of lymph node metastasis, distant metastasis, lymphatic invasion, and stage in colorectal cancer." (PMID 27924922, 2016). "GLUD1 and SLC25A13 were associated with tumor aggressiveness and poorer prognosis of colorectal cancer." (PMID 27924922, 2016). "GLUD1 and SLC25A13 have pivotal roles in nutritional stress and are associated with tumor aggressiveness and poorer prognosis of colorectal cancer." (PMID 27924922, 2016). "Glutamate dehydrogenase 1 (GLUD1) and SLC25A13 have pivotal roles under glucose-deprived conditions and are associated with tumor aggressiveness and colorectal cancer prognosis." (PMID 27924922, 2016). "Subsequently, the relevance of GLUD1 and SLC25A13 expression in colorectal cancer with respect to clinicopathological characteristics and prognosis was evaluated by immunohistochemistry." (PMID 27924922, 2016). "In the present study, SLC25A13 expression was observed in the glandular cells of normal colorectal tissue and colorectal cancer tissue by immunohistochemistry." (PMID 27924922, 2016). "In addition, SLC25A13 is correlated with tumor aggressiveness and poorer prognosis of colorectal cancer." (PMID 35607442, 2022). "SLC25A13 was also found to be pivotal in colorectal cancer aggressiveness." (PMID 35607442, 2022). "Other metabolic alterations that are observed to be related to colorectal cancer initiation are the overexpression of GLS1, GLUD1, and the mitochondrial aspartate glutamate carrier 2 (SLC25A13), which are associated with tumour growth and poorer outcome in colon cancer." (PMID 33915900, 2021). "In conclusion, GLUD1 and SLC25A13 may serve as new targets in treating refractory colorectal cancer which survive in malnutritional microenvironments." (PMID 27924922, 2016). "Furthermore, SLC25A13 was profoundly correlated with colorectal cancer prognosis." (PMID 27924922, 2016). "Taken together, colorectal cancer cells that can adapt to nutritional stress via regulation of GLUD1 and SLC25A13 contribute to tumor aggressiveness and result in worse prognosis." (PMID 27924922, 2016).
Hypoglycemia (3 papers, 2020 to 2025). A decreased concentration of glucose in the blood. "This was accompanied by more severe hypoglycemia and hyperlactatemia in TNF-treated Slc25a13-/- mice, which was not yet evident in TNF-treated wildtype controls at this 8h post TNF timepoint." (PMID 41132685, 2025).
urea cycle disorder (3 papers, 2016 to 2025). A genetic inborn error of metabolism characterized by the deficiency of one of the enzymes necessary for the urea cycle. "A customized capture array (NimbleGen, Roche, USA) was designed to capture genes including the six recognized urea cycle disorder genes plus SLC25A13 and SLC25A15, encoding citrin and mitochondrial ornithine transporter, respectively, both of which play important roles in the urea cycle." (PMID 26843370, 2016).
colon cancer (2 papers, 2021 to 2022). "The mutation of SLC25A13 in colon cancer was suggested to have the most significant effect on its expression." (PMID 36254139, 2022). "In colon cancer, both the expression of SLC25A13 and SLC25A9 could be affected by their mutation." (PMID 36254139, 2022).
depression (2 papers, 2024 to 2025). "Interestingly, reduced hippocampus Slc25a13 has been associated with anxiety or depression‐like behaviors in mice, highlighting the role of mitochondrial dysfunction in pathologic behaviors." (PMID 40741980, 2025). "Patients with polymorphisms in another neighbour region, at the D7S1812 locus within the SLC25A13 gene, often present epilepsy, schizophrenia or depression symptoms." (PMID 39120293, 2024).
liver disease (2 papers, 2021). "ATP7B, SLC25A13, and G6PC were the top three genes related to monogenic liver disease in this study." (PMID 33763395, 2021).
melanoma (2 papers, 2021 to 2022). A malignant, usually aggressive tumor composed of atypical, neoplastic melanocytes. "Next, plasma cfRNA samples from melanoma patients (N = 18) versus control plasma of healthy donors (N = 18) were used to determine gene expression levels of six gene candidates (KPNA2, DTL, BACE2, DTYMK, E2F3 and SLC25A13) that showed excellent diagnostic accuracy (AUC >90.0%) in tissue." (PMID 36320118, 2022). "Receiver operating characteristic (ROC) curves showed an area under the curve (AUC) >90.0% for KPNA2, DTL, BACE2, DTYMK, E2F3 and SLC25A13, >80.0% for CCNA2, FOXM1, KIF4A, SLC45A2, COPS8, SLC45A13 and 70.0% for CDC25A and LINC00520; all significantly discriminating melanoma from benign nevi." (PMID 36320118, 2022).
arthropathy (1 paper, 2024). Any disorder of the joints. "Targeting SLC25A13, while potentially lowering the risk of T2DM, may lead to neutropenia and a range of musculoskeletal diseases, such as arthropathy, intervertebral disc degeneration, and joints disorders." (PMID 39280009, 2024).
brain tumours (1 paper, 2021). "Interestingly, expression of ASL, GATM, ODC, SLC25A13 and SLC25A15 is increased in tumours compared to normal brain tissue, indicating that the arginine biosynthesis pathway could be highly active in human brain tumours." (PMID 33809510, 2021).
cardiomyopathy (1 paper, 2021). A disease of the heart muscle or myocardium proper. "Other studies focusing on a Han population found an association between a prognosis of heterogeneous cardiomyopathy with SNPs associated with LGALS3, AGCT, SLC25A13, HRG, APOB, SOD3, SYNM, and TLN2." (PMID 34572079, 2021).
familial cancer (1 paper, 2023). "The frequencies of several detrimental variants of cancer‐related genes (such as GJB2 and SLC25A13) were higher in the non‐familial cancer group than the familial cancer group." (PMID 35861108, 2023).
Fanconi anemia (1 paper, 2022). Fanconi anemia (FA) is a hereditary DNA repair disorder characterized by progressive pancytopenia with bone marrow failure, variable congenital malformations and predisposition to develop hematological or solid tumors. "KEGG pathway analysis showed that SLC25A13 positively regulated Fanconi anemia pathway, cell cycle, DNA replication, basal transcription factors and negatively regulated natural killer cell-mediated cytotoxicity and antigen processing and presentation." (PMID 35607442, 2022).
hearing loss (1 paper, 2016). "SLC25A13 contains the intragenic enhancer hs1642, which has been associated with hearing loss." (PMID 27291887, 2016).
lipid metabolism disorders (1 paper, 2015). "Bioinformatics analysis using IPA tools showed association of most altered proteins with mitochondrial dysfunction and lipid metabolism disorders and were clearly clustered with beta-2-adrenergic receptor (ADRB2), citrin (SLC25A13), and apolipoprotein A1 (APOA1)." (PMID 26030409, 2015).
methylmalonic acidemia (1 paper, 2021). A genetically heterogenous inherited disorder characterized by abnormalities in the metabolism of lipids and proteins. "Some hotspot mutations were observed for several IEMs, including PAH gene c.728G>A for phenylketonuria; MMACHC gene c.609G>A and c.567dupT, MMUT gene c.323G>A for methylmalonic acidemia and SLC25A13 gene c.852_855del for citrin deficiency." (PMID 33514801, 2021).
ovarian carcinoma (1 paper, 2022). A malignant neoplasm originating from the surface ovarian epithelium. "Relatively high mutation rates were also observed in ovarian cancer cell lines for SLC25A13, SLC25A24, SLC25A41, and SLC25A23 and in skin cancer cell lines for SLC25A13, SLC25A8, and SLC25A12." (PMID 36254139, 2022).
Tyrosinemia type 1 (1 paper, 2019). "Genetic testing results takes weeks or months, but polymerase chain reaction (PCR) sreening for hot-spot mutations in SLC25A13 gene, serum pancreatic secretory trypsin inhibitor (PSTI), and blood/urine succinylacetone will differentiate most cases of NICCD from tyrosinemia type 1 within days." (PMID 30642297, 2019).
uterine corpus endometrial carcinoma (1 paper, 2022). A endometrial carcinoma (disease) that involves the body of uterus. "Almost all SLC25s had high mutation frequency in uterine corpus endometrial carcinoma, including SLC25A12, SLC25A13, SLC25A14, SLC25A23, SLC25A24, and SLC25A25." (PMID 36254139, 2022).
cancer (10 papers, 2016 to 2024). A tumor composed of atypical neoplastic, often pleomorphic cells that invade other tissues. "SLC25A13 c.852_855delCATA (n = 7), GJB2 c.235delC (n = 7), and PALB2 c.C2257T (n = 2) were the variants observed more than once across cancers." (PMID 33889545, 2021). "On the contrary, SLC25A23 and SLC25A13 had medium-to-low protein expression levels in some cancer." (PMID 36254139, 2022). "Thus, it is of importance to reveal the role of SLC25A13 in cancer development and evaluate the prognostic value of immunotherapy of SKCM patients." (PMID 35607442, 2022). "Since HepG2 are hepatocarcinoma cells we wondered whether the SLC25A13 gene was also under-expressed in cancer." (PMID 30995827, 2019). "After analyzing the frequencies of P/LP variants on GJB2 and SLC25A13 genes, we suggest that these two genes may not be cancer‐related genes and need be re‐evaluated." (PMID 35861108, 2023). "However, there are only a few studies that have examined the relevance of SLC25A13 to cancer." (PMID 27924922, 2016). "Meanwhile, SLC25A13 and its neighboring genes were enriched in transcription factor target genes, including MEF2C, NCOA2, SNAI1, and SOX10 target genes, which were participated in the cancer progression." (PMID 35607442, 2022). "Interestingly, the correlation between expression of the functionally identical AGC2 (SLC25A13) isoform and patient survival was usually in the opposite direction of AGC1 within the same type of cancer." (PMID 33292758, 2020). "Therefore, we suggest that GJB2 and SLC25A13 may not be cancer‐related genes according to the results of statistic test." (PMID 35861108, 2023). "As cancer cells rely on lactate dehydrogenase and cytosolic malate dehydrogenase 1 in regenerating cytosolic NAD+, a downregulation of SLC25A13 does not compromise HCC cell survival." (PMID 30995827, 2019).
tumours (9 papers, 2015 to 2023). "Functional enrichment analysis of SLC25A13 showed that it was associated with tumor development and progression." (PMID 35607442, 2022). "Although expression of neither of the two antiporters, SLC25A12 and 13, was increased in SDH-deficient cells, protein expression of SLC25A13 was noted as significantly upregulated in SDH-deficient tumours." (PMID 26522426, 2015). "Notably, high GLUD1 expression combined with low SLC25A13 expression had a higher association with tumor aggressiveness than did individual expression of each." (PMID 27924922, 2016). "SLC25A13 plays a pivotal role under glucose-deprived conditions and is correlated with tumor aggressiveness." (PMID 35607442, 2022). "As SLC25A13 could be a biomarker for tumor immune cell infiltration in SKCM, the feasibility of exploring SLC25A13 as a biomarker of psychological intervention in SKCM treatment might need further investigation." (PMID 35607442, 2022). "In addition, the expression of SLC25A13 was negatively correlated with the tumor-infiltrating cells in the tumor immune microenvironment." (PMID 35607442, 2022). "High GLUD1 expression or low SLC25A13 expression was found to be associated with tumor aggressiveness, including depth of tumor invasion, lymph node and distant metastasis, lymphatic and venous invasion, and stage." (PMID 27924922, 2016). "While ASS1 was found to be downregulated in GBM tumours and NCH644 NS cultures, the expression of ODC1, SLC25A13 and SLC25A15 was increased." (PMID 33809510, 2021). "Our findings demonstrate that FOXA2 downregulates SLC25A13 expression and function, in agreement with the reported role of FOXA2 as tumour suppressor in HCC." (PMID 30995827, 2019). "Gene Ontology (GO) and Kyoto Encyclopedia of Genes and Genomes (KEGG) analysis of SLC25A13 coexpressed genes showed that these genes are enriched in ATPase activity, cell cycle, mTOR, and VEGFA-VEGFR2 signaling pathways, which were relevant to tumor development and angiogenesis." (PMID 35607442, 2022).
hematological disease (1 paper, 2022). "In addition, genes associated with hematological disease (e.g., PDE7A, LMAN1, F13A1, OLR1) and mitochondrial biogenesis and redox (e.g., NOS3, ALDH5A1, PRXL2A, SLC25A13, CPT2) were also significantly altered in BPD patients." (PMID 35484630, 2022).
SLC25A13 also shares sentences with these, for which no sentence is quoted: Hyperammonemia (16 papers); metabolic disease (8); dyslipidemia (5); Failure to thrive (4); Coma (3); genetic diseases (3); phenylketonuria (3); beta thalassemia (2); cholestasis (2); epilepsy (2); liver cancer (2); Obesity (2); ornithine carbamoyltransferase deficiency (2); tyrosinemia (2); Wilson disease (2); 5-alpha reductase deficiency (1); Alpha-thalassemia (1); Alzheimer disease (1); amino acid metabolic diseases (1); Anxiety (1); Argininemia (1); autism (1); cervical cancer (1); cholangiocarcinoma (1); Cholestatic jaundice (1); deafness (1); delirium (1); developmental arrest (1); dyslipidaemia (1); edema (1).
A further 24 diseases each share a sentence with SLC25A13 in 1 paper.